MIR4744 (microRNA 4744)
Synonyms: hsa-mir-4744
Gene: MicroRNA gene on chromosome 18 (49,049,687 to 49,049,768, reverse strand). Ensembl gene ENSG00000263849.
Homologues: Orthologues: chimpanzee MIR4744 (100% identical).